CD4 (CD4 molecule)
Diseases named in the same sentence as CD4 in open-access papers (continued):
Sharing a sentence is not in itself a finding about the gene and the disease.
cancer (continued). "Based on CD4+/CD8+ T cell recognition, the TERT vaccine presents a promising therapeutic efficacy in a proportion of cancer, although its safety and universal applicability in different types of cancer requires further research and verification." (PMID 38278800, 2024). "By fusing a DNA fragment encoding TT to the DNA cancer vaccine, an intense immune response mediated by CD4+ and CD8+ T-cells can be induced against the self-antigen which can, in turn, improve the clinical profile of cancer patients." (PMID 39872522, 2024). "Given that CLEC2D induction requires robust and sustained immune activation, it would be interesting to investigate the potential of CD4+LLT1+ T cells as peripheral blood predictive biomarkers for immunotherapy responses and cancer remission." (PMID 38675738, 2024). "To verify this conjecture, we carried out polychromatic immunofluorescence on 8 markers, including cancer cells (CK18), T cells (CD3, CD4, CD8 and CD 29), SAMD4B, PD1 and PD-L1." (PMID 38886351, 2024). "Increased GJB3 expression was associated with different types of immune cells, including T cells CD4, T cells CD8, neutrophils, macrophages, and dendritic cells (DC) in various cancer types." (PMID 38728250, 2024). "CD4+ and CD8+ T cells represent two broad classes of T cells crucial for immune responses against infection and cancers and distinguished by divergent recognition and effector mechanisms." (PMID 39627220, 2024). "Recent research highlights the significance of both CD4+ T cells, CD8+ T cells, and B cells in the field of cancer immunotherapy." (PMID 38392302, 2024). "Our TIMER-based investigation found a significant correlation between LRP1 levels and various immune cell types, including B cells, CD4+ and CD8+ T cells, neutrophils, macrophages, and dendritic cells across multiple cancer types." (PMID 39063239, 2024). "The process involves the presentation of cancer cell antigens by antigen-presenting cells and the activation of CD8+ T cells that directly kill the cancer cells; the CD4+ T cells provide helper signals." (PMID 38756774, 2024). "NSG2 expression positively correlated with CD4+ T cells, CD8+ T cells, and Lamp3+ dendritic cells in both cancer and stromal compartment, but negatively correlated with CD20+ B cells in stromal cells." (PMID 39493764, 2024). "Evidence has shown the significant prognostic value of the abundance of CD4 + and CD8 + T cells in cancer patients." (PMID 38173048, 2024). "To further validate this immune correlation and elucidate the role of SPOP in cancer progression, we further assessed the correlation between SPOP expression level and CD4+ T cell as well as CD8+ T cell infiltration level by immunohistochemistry." (PMID 39074086, 2024). "T-cell exhaustion is a complex immune cell deficit observed in viral and bacterial infections and in cancer where there is overexpression of multiple inhibitory receptors and impaired production of effector cytokines such as INFγ in CD8+ and CD4+ T-cells." (PMID 37847301, 2023). "We uncovered that CDKN2A was positively correlated with infiltration degree of CD4+ T cells, NKT cells, Tregs, MDSC, neutrophils and macrophages in most TCGA cancers." (PMID 36961395, 2023). "Previous studies have shown that CD4 + and CD8 + T-cell responses are part of the cancer-immune cycle and that both parts can significantly influence the clinical outcome." (PMID 36949429, 2023). "CD4+ T-cell depletion reduces the number of activated CD8+ T cells and abrogates the protective effect of cancer cell class II expression." (PMID 37565053, 2023). "One cycle of FMD + VC shifted T cell populations toward anti-cancer immunity, increasing the pool of CD3+CD8+ in all three compartments, while reducing the pool of CD3+CD4+ cells in the bone marrow and spleen." (PMID 38136414, 2023).
cancer (continued). "Significant increases in Th1 cells (CD4+IFN-γ+), Treg cells (CD4+CD25+CD127−), and Th17 cells (CD4+IL-17+) were observed in malignant ascites compared with the corresponding blood." (PMID 36690649, 2023). "The results showed that the characteristics of PAMcluster-A which had the best survival probability and related immune infiltration of CD4 + and CD8 + T cells, and weak expression of most cancer pathways within it." (PMID 37202800, 2023). "In this present study, our findings indicated that the expression of RNF43 was related to several immune cells, such as dendritic cells, T cells CD4, T cells CD8, plasma cells, macrophages, and B cells in various cancer types." (PMID 37848933, 2023). "Nevertheless, the impact of the balance between CD4+ T and CD8+ T in peripheral blood of cancer patients on ICI therapies is still unclear." (PMID 37974194, 2023). "Immune cell infiltration, particularly of CD4+ or CD8+ T cell, B cell, monocyte, macrophage, dendritic cell, and NK cell infiltration, develops in lockstep with progressive cancerization of breast tissues." (PMID 36951624, 2023). "We conclude that correlations between TAP1 expression and four specific lymphocyte populations (activated CD4+ T, CD8+ T, B, and NK cells) infiltration levels were evident in 12 types of cancer in which TAP1 has a protective role." (PMID 36759763, 2023). "Expression of SOX2 in BCSC recruits the CD4+ regulatory T cells through secretion of CCL1, where Tregs further promote cancer cell stem properties." (PMID 37445860, 2023). "The importance matrix ranking results for the ANN prediction model were hypoproteinemia, HGB/RDW, cancer, LDL-C, CD4+ T cell count, electrolyte disturbance, Cl, Ccr, HCO3std, Mono/Lymph, GGT and Cys-C." (PMID 37575113, 2023). "The numbers of PD-L1+ CD4+T, CTLA-4+ CD4+T, PD-L1+ CD8+ T, and CTLA-4+ CD8+ T cells increased as the cancer stage increased." (PMID 37153541, 2023). "The predominant subtypes of CD4+ cells are TH1 and TH2, but TH1 cells are regarded as the most important for cancer immunity." (PMID 37240369, 2023). "We investigated correlations of immunosuppressive markers (e.g., PD-L1, CTLA-4, and IL-10) in CD4+ and CD8+ T cells from cancer mucosa of GC patients." (PMID 37153541, 2023). "PD-1 and PD-L1 in CD4+/CD8+ T cells, DCs, macrophages and MDSCs were detected to be upregulated in different RT parameters and cancer species." (PMID 37833255, 2023). "The presence of PD-L1 in melanoma cell-derived exosomes further supports a systemic immunosuppressive effect, whereby CD4+ and CD8+ T lymphocytes are reduced and cancer cell clearance is impeded." (PMID 37189748, 2023). "FOXP3 expression does not equate strictly to Treg identity and has also been described in CD4+CD25−T cells, and cancer cells." (PMID 38077395, 2023). "Results of the CIBERSORT and CIBERSORT-ABS algorithms showed that there were positive correlations between activated CD4+ memory T cells, resting subsets, and GOLT1B expression in most cancer types such as BRCA and SKCM." (PMID 38130634, 2023). "NNMT significantly correlated with the infiltration levels of B cells, CD4+ T cells, CD8+ T cells, macrophages, NK cells, and neutrophils in diverse cancers." (PMID 36817086, 2023). "Although more highly expressed in CD4 T cells, OX40 engagement promoted both CD4 and CD8 T cell responses in cancer patients." (PMID 37189417, 2023). "In this study of recently immunized cancer patients, the BNT162b2 and the BBIBP-CorV vaccine induced significant neutralizing IgG antibody titer and a CD4+/CD8+ T-cell response against SARS-CoV-2." (PMID 37515127, 2023). "Conceivably, the immunogenicity of cancer vaccines can be further enhanced to induce even stronger cytotoxic T cell (CTL) and CD4 + T helper cell responses." (PMID 37222770, 2023). "However, whether cytotoxic CD4+ T cells play a role in HPV-driven cancers is unknown." (PMID 36512410, 2023).
cancer (continued). "The researchers report an increase in CD4+ T cells, CD8+ T cells, CD3+ T cells, NK cells, macrophages, and M1 macrophages in intratumour tissue in cancer patients who received vitamin D supplementation." (PMID 37299554, 2023). "MYB had a strong correlation with B cell in 24 cancer types, CD4 T cell in 22 cancer types, CD8 T cell in 18 cancer types, neutrophil in 25 cancer types, macrophage in 13 cancer types and DC in 24 cancer types." (PMID 36994664, 2023). "As was shown in a meta-analysis study across different cancer types, RT resulted in a systemic reduction of CD3+ and CD4+ peripheral T cells one month after the last treatment." (PMID 37006319, 2023). "HHI therapy appeared to upregulate MHC class I expression and increase infiltrating immune cells (CD8+, CD4+, HLA-DR-class II+ mononuclear cells, and CD68+ macrophages) at the cancer site." (PMID 37887561, 2023). "An obviously decreased absolute numbers were observed in cancer patients, including CD45+, CD3+ T, CD3+CD4+ Th, CD3+CD8+ CTL, CD16+CD56+ NK and CD19+ B cells (P < 0.0001)." (PMID 38102684, 2023). "CD4 + and CD8 + cells were observed both in cancer stroma and within cancer epithelium (i.e., intraepithelial)." (PMID 37277702, 2023). "Activate CD4+ immune response and stimulate T-helper cells against HER2/Neu expressing cancer cells." (PMID 37492478, 2023). "CD4, Fibronectin, CD27, CD11c, and IDO1 were the protein markers from ‘immune-rich cancer cell islets’ and ‘surrounding stromal leukocyte’ regions linked with a significant hazard ratio and overall survival." (PMID 37046826, 2023). "After adjusting for confounders, patients with CD4 count ≤500 cells/mm3 at baseline had higher hazards of OIs [AHR (95% CI) = 2.3 (2.0–2.6)] and malignancies [AHR (95% CI) = 1.2 (1.04–1.4)]." (PMID 37824698, 2023). "While most cancer immunotherapies have focused on CD8+ T cells as the main drivers of antitumor immunity, increasing evidence indicates that CD4+ T cells also play a central role in the elimination of tumors." (PMID 36980536, 2023). "Here, we conducted a detailed characterization of CD4+ T cells and CD8+ T cells in malignant effusion including peritoneal ascites and pleural fluid from thirty-five patients with malignant tumor and compared with results from matched blood." (PMID 37215450, 2023). "Of note, the cancer group had higher percentage of CD3+CD8+ CTL (median: 24.7% vs. 22.8%, p = 0.0003) and lower ratio of CD4+/CD8+ T cells than the healthy control (median: 1.496 vs.1.67, p = 0.0007)." (PMID 38102684, 2023). "Our results demonstrated that ABI3 expression manifested a positive correlation with the infiltration levels of CD4+ T cells, CAFs, Endo, HSCs, γ/δ T cells, NK T cells, Tregs, B cells, monocytes, and CD8+ T cells in the majority of the TCGA cancers." (PMID 37942289, 2023). "The expression levels of IGSF6, CD8+ T cells, CD4+ T cells and CD68+ macrophage cells in cancer tissues from CRC patients and CRC cell lines were evaluated." (PMID 37989761, 2023). "Following that, we searched the relationship between SLC25A1 expression and infiltration level of 6 immune cell types (CD4 + T cells, CD8 + T cells, neutrophils, myeloid dendritic cells, macrophage, and B cells) in pan-cancer from the TIMER database." (PMID 37981593, 2023). "The activation of cancer antigen-specific CD8+ T and CD4+ T cells is a critical issue for the efficacy of cancer vaccines." (PMID 37509288, 2023). "On the other hand, regulatory T cells (Treg cells) can suppress the functions of CD4+ and CD8+ T cells, contributing to immune suppression in cancer." (PMID 38041544, 2023). "In another clinical trial, recombinant human IL‐7 injection every other day for 2 weeks in refractory cancer patients increased CD3+, CD4+, and CD8+ lymphocytes in a dose‐dependent manner." (PMID 36583472, 2023).
cancer (continued). "There was a significant correlation between the CD4+ subsets of T cells and GOLT1B expression in TGCT and OV, two cancer types with the highest alteration frequency of copy number of sCNA." (PMID 38130634, 2023). "For lymphoid immune cells, the expression of NRP1 was negatively correlated with the infiltration of B and T helper (Th) 1 cells, CD4+T central memory (Tcm), and NKT cells in almost all cancers, and NRP2 presented similar results." (PMID 37190154, 2023). "For example, SERPINA1 expression was closely related to CD4+ T cells, CD8+ T cells, neutrophils, and macrophages in most cancer types." (PMID 37511325, 2023). "The xCell algorithm also provided the corresponding analysis: the strongest negative correlation between T cell CD4+ Th1, Th2 and T cell CD4+ central memory cells and the presence of ABI3BP expression in various cancers." (PMID 37197424, 2023). "One strategy involves using cancer-testis/cancer-germline antigens such as NY-ESO-1, which are proteins aberrantly expressed in OC, and have demonstrated consistent CD4+ and CD8+ T-cell responses in OC patients leading to prolonged responses." (PMID 38164130, 2023). "In most TCGA cancers, CDKN2A is positively correlated with the degree of infiltration of CD4+ T cells, NKT cells, Tregs, neutrophils, and macrophages." (PMID 36961395, 2023). "To investigate this possibility, we treated sorted CD4+T and CD8+T cells with cfChPs (10ng) from cancer patients and performed a time course analyses using qRT-PCR to detect 5 immune checkpoints." (PMID 38274821, 2023). "With cancer moving to advanced stage, the percentage of PD-1+CD45+ cells, PD-1+CD3+ T cells, PD-1+CD4+ Th cells showed an increased trend (P < 0.05)." (PMID 38102684, 2023). "In this chapter and its associated four subchapters, we provide an overview of the expression of lncRNAs in T cell subsets (CD8+ T cells, CD4+ T cells, regulatory T cells, γδ T cells and NKT cells) during homeostasis and cancer." (PMID 37346034, 2023). "IL-10 and IL-35 are immunosuppressive cytokines produced by Tregs that inhibit effector immune cells (i.e., CD4+ and CD8+ T cells), therefore protecting the cancer cells from immune surveillance." (PMID 37190281, 2023). "Immunofluorescence images showed higher expression levels of immunosuppressive markers, such as PD-L1 and CTLA-4, in CD4+ and CD8+ T cells from cancer mucosa of GC patients as the cancer stage increased." (PMID 37153541, 2023). "These cells were subsequently clustered into 10 cell subgroups, including kidney epithelium, CD4 + T cell, CD8 + T cell, myeloid cell, endothelial cell, cancer cell, NK cell, fibroblast, B cell, and mast cell by identified the marker genes." (PMID 36765369, 2023). "A recent study correlated increased HPSE expression with higher immune infiltration levels of CD4+ and CD8+ T cells, macrophages, neutrophils, and dendritic cells in cancer." (PMID 37115924, 2023). "The findings revealed a positive correlation between KIFC1 expression and the infiltration levels of CD4+ T cells, CD8+ T cells, myeloid-derived suppressor cells (MDSCs), T follicular helper cells (Tfh), and macrophages in the majority of TCGA cancers." (PMID 38112634, 2023). "In co-culture of these cells (RKO OKT3) with human PBMCs, we found that GB265, GB266, and GB266T with wildtype IgG1 Fc outperformed parental antibodies in the promotion of cancer cell killing, CD8 T cell expansion, and CD4 T cell expansion." (PMID 37332070, 2023). "CD4+ T-cells and CD68+ macrophages predominate in the stroma around the invasive cancer margin in these lesions." (PMID 36980751, 2023). "The anti-cancer effect of CD8 T cells, activated CD4 T cells, and activated NK cells have been verified in multiple cancers." (PMID 37584707, 2023). "The fact that KCNJ14 primarily affects the infiltration of CD4+ and CD8+ cells was first reported in CRC, which is of importance because CD4+ T cells play a major role in controlling the cancer immune microenvironment." (PMID 36768373, 2023).
cancer (continued). "In line with previous studies, our results displayed declined cell counts of CD45+, CD3+ T, CD3+CD4+ Th, CD3+CD8+ CTL, CD16+CD56+ NK and CD19+ B in cancer patients." (PMID 38102684, 2023). "The immune response to cancer depends on efficient cytotoxic T lymphocytes (CTL), conventional CD4+ T cells and B cells and checkpoint inhibition therapy is aimed at reinvigorating local cytotoxic T cells." (PMID 37648263, 2023). "In the present study, we tested this notion experimentally using model systems and further investigated the translational feasibility of such an approach using primary human CD4+ and CD8+ T cells transduced with clinically relevant cancer-targeting TCRs." (PMID 37390984, 2023). "Overall, an important condition for success of a cancer vaccine is the induction of a robust and sustained of both specific CD8+ and CD4+ T cells response as well as the increase in the CD4+:Treg ratio, to counteract the immunosuppressive TME." (PMID 37654484, 2023). "Research in other types of cancer, including BCC, shows that CD4+ T cells play an anti-tumorigenic role." (PMID 37173918, 2023). "The CD4+, CD8+ and tetramer+CD8+ T cell populations in splenocytes in FeMOF-based cancer vaccines in large size (OVA-ML) and small size (OVA-MS) are significantly higher than saline group and free OVA group." (PMID 38259474, 2023). "The expression rates of ITGA2, CD4, and CD8 were found to be significantly higher in cancer tissues compared to adjacent tissues." (PMID 37881431, 2023). "In preclinical and clinical studies of personalized cancer vaccines, epitopes selected for binding to MHC-I perhaps surprisingly predominantly gave rise to CD4+ T cell responses." (PMID 37400675, 2023). "In contrast, IHC for effector immune cells revealed that ACT with SRC-3 KO Tregs significantly increased the number of CD4+ T cells, CD8+ T cells, and NK cells in cancers compared to ACT with wild-type Tregs." (PMID 37253006, 2023). "A clinical trial of daclizumab was performed in patients with metastatic BC, in combination with an experimental cancer vaccine, and robust CD8+ and CD4+ T cell priming and the boosting of vaccine antigens were observed." (PMID 37251931, 2023). "CD4+ T cells and CD8+ cytotoxic T lymphocytes (CTLs) are critical immune cells that play critical roles in cancer development and immunity." (PMID 37848933, 2023). "Furthermore, MTHFD2 was observed to be positively correlated with infiltrations of several immune cells in various cancers, especially the activated CD4+ T cell and type 2 T helper cell, which were significant in almost all cancers, suggesting that MTHFD2 might be related to the inflamed TME." (PMID 38130721, 2023). "In pan-human cancers, a high cytotoxic CD38+CD39+CD4+ T-cell gene signature correlates with better clinical prognosis." (PMID 36869048, 2023). "Cancer neoantigens are frequently restricted to MHC II and recognised by CD4+ T cells in both mice and humans." (PMID 37386922, 2023). "In cancer patients, TIM-3 overexpression can be detected on most immune cells, particularly antigen-specific CD8+ T cells, CD4+ T cells, and NK cells." (PMID 37670328, 2023). "The combination of daclizumab and cancer vaccine can induce a robust CD8+ and CD4+ T cell priming and boosting and a decline of Treg cells." (PMID 37829505, 2023). "WT1-specific CD8+ and CD4+ T cells activated by the HLA-antigen complex then migrate to the TME, where they attack WT1-positive cancer cells and exhibit an antitumor effect." (PMID 36138335, 2023). "The numbers of CD4+ and CD8+ T cells, as well as the expression levels of their immunosuppressive markers, were greater in cancer mucosa than in normal mucosa." (PMID 37153541, 2023). "T cell immunoreceptor with Ig and ITIM domains (TIGIT) is expressed on CD4+/CD8+ T cells, NK cells and Tregs and represses immune cells at multiple steps of the cancer immunity cycle." (PMID 37833255, 2023).